MYC (MYC proto-oncogene, bHLH transcription factor)
Diseases named in the same sentence as MYC in open-access papers (continued):
Sharing a sentence is not in itself a finding about the gene and the disease.
cancer (continued). "A number of studies point to the role of MYC in both circadian disruption and cancer as it is a key player in cancer metabolism." (PMID 35984550, 2022). "The results found that PSAT1 can be enriched into the classic signaling pathways of cancer such as mTORC1 signaling, MYC targets and JAK STAT3 signaling." (PMID 36105075, 2022). "MYC proteins are among the most studied oncogenes, and they are dysregulated in more than 50% of cancers with diverse origins." (PMID 36408158, 2022). "Another study has concluded that curcumin downregulates cancer stemness by inhibiting the PRC2/lncPVT1/c-MYC pathway, increasing the sensitivity of pancreatic cancer cells to gemcitabine." (PMID 35965522, 2022). "Pharmacological inhibition of CTP synthase induces selective replication stress in MYC‐overexpressing cancer cells and synergizes with ATR inhibitors to kill them." (PMID 36214609, 2022). "The MYC pathway not only determines cancer cell pathophysiology but also suppresses host immune responses." (PMID 35996406, 2022). "Specifically, we observed a downregulation of common cancer-related gene sets, such as MYC target genes and genes involved in an ESC-like signature." (PMID 35453756, 2022). "MYC is one of the most widely studied oncogenes involved in the growth, progression, and maintenance of various cancer types." (PMID 36482116, 2022). "MYC is known to cooperate with KRAS in driving many cancers and contributes to many cancer hallmarks." (PMID 35883603, 2022). "As it occurs in other cancers, MYC stimulates the Warburg effect in MB by directly trans-activating the expression of key glycolytic genes." (PMID 36340043, 2022). "Multiple cancer-associated genes are significantly downregulated in the translatome upon shMSI1 inhibition, including MAP3K13, transcriptional enhancers of MYC and genes essential in early development, NPM1 and KMT2A, respectively." (PMID 36473869, 2022). "c-MYC belongs to the “super transcription factors” family and is deregulated in >50% of cancers, which is an important target for cancer therapy." (PMID 36237336, 2022). "Evidence of ecDNAs has been found in many other cancer types and involves a genome fragment, often containing a small oncogene such as MYC, which is excised and amplified." (PMID 36230545, 2022). "c-MYC is a transcription factor reported to constitutively and aberrantly expressed in more than 70% of human cancers, and has attracted enormous public efforts in identifying new small molecule inhibitors for therapeutic use in clinics." (PMID 35941699, 2022). "Overexpression of EIF4EBP1 in cancer is mediated by certain transcription factors, such as MYC, androgen receptor, and the stress regulators ATF4 and HIF-1α, which all bind to and thereby modulate the activity of the EIF4EBP1 promoter." (PMID 35379801, 2022). "The combination of N-acetylcysteine (NAC) and vitamin C was found to prevent the onset of cancer in a model of MYC-dependent human B lymphoma." (PMID 35530337, 2022). "MYC oncogene is a target gene of Wnt signaling pathway, which is constitutively activated in the early development of various cancers including CC." (PMID 35814404, 2022). "Second, MYC also enhances rDNA transcription by binding at the promoters of the RNAPolI cofactors SL1, UBF, and TIF-1A, which are often elevated in cancers, likely resulting from MYC transcriptional activity." (PMID 35159381, 2022). "Cancer cells often acquire tumor-specific SEs at vital oncogenes, such as MYC, which induce several hallmarks of cancer." (PMID 35159127, 2022). "Hopefully, MYCMI-7 together with other MYC inhibitors can pave the way for the development of clinically relevant anti-MYC therapy for these and other types of cancer in the future." (PMID 36874405, 2022).
cancer (continued). "A previous study has demonstrated that CLK2 inhibitor T-025 has antitumor efficacy in many tumors, especially in MYC-driven cancers." (PMID 35860803, 2022). "MYC overexpression is related to many hallmarks of cancer, ranging from immunosuppression to metabolic and epigenetic reprogramming." (PMID 36611833, 2022). "Exosomal miR-105 is stimulated by the oncoprotein MYC in cancer cells and promotes MYC signaling in CAFs to drive a metabolic program." (PMID 36338993, 2022). "MYC is a proto-oncogene that potently drives tumorigenesis and is the most commonly amplified gene in human cancer." (PMID 36018850, 2022). "A large body of evidence supports the idea that MYC can profoundly shape the metabolic state of cancer cells by regulating a plethora of processes such as glutamine synthesis, glycolysis and lipogenesis as well as mitochondrial biogenesis and metabolism." (PMID 36340043, 2022). "Among them, five cancer-associated genes were confirmed by both analyses as the most frequent genes with gains: NOTCH1, MYC, NUMA1, PLAG1, and RAD21." (PMID 35884575, 2022). "On one hand, MYC is an FBXW7 target that stimulates mitochondrial biogenesis, and increased levels of MYC have been shown to correlate with increased resistance to certain cancer therapies." (PMID 35861150, 2022). "To learn more, about the consequences of the RelA T505A mutation on the DNA replication response in cancer, we decided to investigate its effect in a cancer model driven by the MYC oncogene, the Eμ-Myc model of B-cell lymphoma." (PMID 36240065, 2022). "Virtually all tumors besides CRC display deregulated MYC expression and activity, arguing that approaches to identify critical pathways in MYC‐driven cancers have enormous therapeutic potential." (PMID 35673898, 2022). "These authors presumed that the cancer-specific iPCCs were subjected to genetic instability via genetic or epigenetic alterations, including oncogenic activation of c-MYC." (PMID 35629138, 2022). "The MYC oncogene is deregulated in 70% of cancers, including CRC, and amplified in about 20% of CRC patients." (PMID 35158939, 2022). "This is in line with previous observations in other cancer types and with the idea that MYC is indispensable for the proliferation of all cancer cells." (PMID 36860495, 2022). "USP28 levels are increased in cancer compared with in normal cells due to a feed‐forward loop, driven by increased amounts of oncogenic transcription factors such as c‐MYC and c‐JUN." (PMID 35364627, 2022). "Previous studies suggested that the MYC oncogene is often activated and/or overexpressed in cancers." (PMID 35501901, 2022). "G-quadruplexes, G4, have been found in telomeric DNA, as well as in the promoter regions of a number of genes, including cancer oncogenes, such as MYC and KRAS." (PMID 35328482, 2022). "c-MYC functions as a master transcription factor in various biological processes by regulating many target genes, and excessive activation of c-MYC is one of the most prevalent oncogenic events in human cancers." (PMID 36457036, 2022). "Targeting MYC for cancer treatment, however, has proved difficult as the protein lacks a suitable site for high-affinity binding of low-molecular-weight inhibitors." (PMID 35908121, 2022). "Further downstream, mitogen-activated protein kinases (MAPK), MYC, and nuclear factor kappa-light-chain enhancer of activated B cells (NF-κB) signaling is involved, pathways that can also be targeted for cancer therapy." (PMID 35883678, 2022). "c-MYC is upregulated in several cancers and the TCGA database shows that 28% of all cancers harbour genetic abnormalities in at least one of the Myc family." (PMID 35681547, 2022).
cancer (continued). "BRD4 is upregulated in diverse types of cancer, resulting in the induction of potent oncogenes such as MYC, c-MYB, ERG, and E2F1." (PMID 35399501, 2022). "The oncogene MYC (also known as c-MYC) is overexpressed in almost all cancers and has become an important oncotarget." (PMID 35453304, 2022). "The MYC oncogene not only drives cancer progression, but also favors resistance to classical chemotherapy and targeted therapies." (PMID 36214609, 2022). "A number of different strategies have been used to suppress the activity of MYC in cancer cells, some of which have progressed to clinical trials as BET inhibitors and G-quadruplex stabilizers (Quarflaxin)." (PMID 35408939, 2022). "Processes significantly influenced the development of cancer, including MYC targets V2, DNA repair, IL-6/JAK/STAT3 signaling, and immune response." (PMID 36226251, 2022). "The relationship between HSF1 and mTOR, also seen in other cancer types, was demonstrated as a necessary component for MYC-driven HCC." (PMID 35311075, 2022). "MYC proto-oncogene boosts the oncogenic transcription amplification process in cancer and is a crucial target for cancer therapy." (PMID 35075228, 2022). "We found that MYC‐related targets, which have aberrant expression in up to 70% of human cancers, were significantly expressed in both cohorts." (PMID 35488454, 2022). "In cancer, however, MYC gene amplification/translocation or aberrant growth factor signaling can cause accumulation of supraphysiological levels of Myc protein." (PMID 36552851, 2022). "The cancer-recurrent substitution MYC S146L occurs within three residues of the highly conserved MB2 region in the MYC TAD, which serves as a critical binding platform for TRRAP." (PMID 36018850, 2022). "Exosomal miR-105 secreted by BCCs induced by the MYC gene of cancer cells induces metabolic programming by activating MYC signaling in CAFs." (PMID 36005690, 2022). "Another group is targeting the eukaryotic initiation factor 4F complex (eIF4F), which regulates the translation of many pro-oncogenic proteins like MYC and cyclins in various cancers." (PMID 35936751, 2022). "Results obtained for FBXO32, ZHX1 and ANXA13 genes encoded within the same region as ATAD2 clearly emphasize the specificity of ATAD2 and MYC as well as ATAD2 and cancer stemness associations." (PMID 35049055, 2022). "Taken together, our results highlight the previously uncharacterized shortening of the MYC 3′UTR in cancer, and identify miR-138 as a potent regulator of the heterogenous MYC transcript population." (PMID 34937878, 2022). "DNA G4 motifs have been found in promoter regions, usually within 1kb upstream of the transcription starting site (TSS), of many cancer-related genes, such as c-MYC, c-KIT, HIF, BCL-2, RET, k-RAS, h-RAS, HSP90, b-RAF, VEGF, hTERT and MDM2." (PMID 35337098, 2022). "In the case of the MYC gene, G-quadruplexes regulate gene expression, including 90% of MYC expression, thus making it a potential drug target for MYC-deregulated cancer." (PMID 35328482, 2022). "The steroid-activated androgen receptor (AR) can also decrease the c-MYC signaling pathway, which accounts for driving reinforced glutaminolysis in cancer cells through regulating glutamine transporters and GLS1 directly or indirectly (via miRNA)." (PMID 36077501, 2022). "As such, c-MYC is a potential drug target in TNBCs and other cancers but has been historically difficult to target directly due to its protein structure and other characteristics." (PMID 36712364, 2022). "Because the MYC oncoprotein is notoriously difficult to target, global inhibition of sumoylation with ML-792 (or with other similar drugs in the pipeline such as TAK-981) deserves attention as a potential therapy in MYC-driven cancers." (PMID 35269436, 2022).
cancer (continued). "We found MYC differentially expressed in 14 out of 21 cancer types, and in those cancer types its targets are significantly enriched among differentially expressed genes (p<0.05, chi-square test)." (PMID 35575458, 2022). "Taken together our data show that KMT2C truncating events drive cancer progression by upregulating MYC target genes and circumventing p16INK4A-mediated growth arrest." (PMID 35354467, 2022). "The oncogene MYC is estimated to contribute to 75% of all human cancers, many of which are aggressive and respond poorly to the current therapies." (PMID 36499669, 2022). "Since its identification over 40 years ago as the human cellular ortholog of the transforming avian v-myc retroviral oncogene, the MYC gene’s aberrant expression has been documented in many human cancer types." (PMID 36552737, 2022). "MYC S146L (sometimes annotated as S161L due to an alternative non-ATG start codon) is the fourth most common somatic substitution in MYC found in cancer." (PMID 36018850, 2022). "Specifically, we found a number of traditional anti-cancer agents showed biological activity only in MYC-enriched cell lines (e.g., 3-CI-AHPC, CD-437)." (PMID 35013227, 2022). "MYC acts as a protooncogene and plays an important role in cancer cell growth, division and metabolism." (PMID 35091546, 2022). "Since siRNA has the ability to reduce the expression of target genes, studies have focused on using siRNA to down-regulate cancer-associated genes, including undruggable genes (e.g., KRAS, MYC)." (PMID 36015212, 2022). "In particular, MYC and ATF4 have been shown to co-regulate EIF4EBP1 transcription in cancer cells, providing one potential mechanism underlying EIF4EBP1 overexpression in cancer." (PMID 35228525, 2022). "Reportedly, KRT6A is associated with cell proliferation and invasion, which drives cancer progression by upregulating glucose-6-phosphate dehydrogenase (G6PD) through MYC signaling pathway." (PMID 36505456, 2022). "According to screening based on the degree centrality, the most critical node for LUSC was Cg25080152, corresponding to the gene MYC, which is a target gene for cancer therapy." (PMID 36676027, 2022). "MYC was found to be elevated in 70% of human cancers, making it one of the most pervasive oncogenes." (PMID 35159381, 2022). "While more work must be done in additional disease-relevant models, our findings represent a clear indication of the potential oncogenic role of MYC S146L in cancer development." (PMID 36018850, 2022). "Initially focusing on common hallmarks, we observed a strong downregulation of MYC target genes, which are of fundamental importance for cell growth and the maintenance of stem cell characteristics in cancer cells." (PMID 35453756, 2022). "The WES also allowed us to identify CNV-seq in 42 cancer-associated genes with cn > 3, including NOTCH1, MYC, NUMA1, PLAG1, and RAD21 amplified in 10% of tumors." (PMID 35884575, 2022). "Although the characterization of the MYC members has been very extensive in the study of different cancer types, its role in neurodegenerative diseases is still far from being understood." (PMID 35328644, 2022). "This is in agreement with other studies reporting that CBL0137 as well as panobinostat attenuate MYC oncogene expression in cancer cells." (PMID 35677155, 2022). "In addition, this data suggests that studying the post-transcriptional regulation of the MYC CDS may lead to the identification of crucial miRNAs that modulate the expression of all MYC transcript variants, including those which are predominantly expressed in advanced cancer." (PMID 34937878, 2022). "To investigate MMCC functional relevance in advanced cancers, we induced clonal MYC overexpression in neoplastic epithelial tissues of Drosophila, observing a significant deviation both in terms of final cell composition and cancer size." (PMID 36704198, 2022).
cancer (continued). "We first examined the promoter region of the MYC proto-oncogene, which is overexpressed in more than 50% of cancers." (PMID 36555662, 2022). "In the present study, we assessed the signaling of NF-κB and MYC with potential therapeutic applications in primary cancer stem cells (CSCs) isolated from GBM." (PMID 36361720, 2022). "In MYC-driven cancers, glutamine deletion impairs the TCA cycle and inhibits cancer cell viability in an energetic-demand mechanism." (PMID 36200045, 2022). "Taken together these results demonstrate that the cancer-recurrent substitution S146L promotes MYC:TRRAP binding." (PMID 36018850, 2022). "IGF2BPs play a carcinogenic effect in cancer cells by stabilizing the methylated mRNA of oncogenic targets (such as MYC)." (PMID 35047058, 2022). "During cancer development, cancer cells can acquire super-enhancers near key oncogenes, such as MYC and TAL1, and several oncogenic super-enhancers have been found across a broad spectrum of cancers." (PMID 36147741, 2022). "Especially in high glycolytic cancers, such as MYC-driven cancers, MCT1 facilitates lactate uptake and PD-1 expression in Tregs, a novel mechanistic view of anti-PD-1 therapy resistance." (PMID 36200045, 2022). "This protein is an important component of the cellular DNA-damage and cell cycle checkpoint response and has been targeted in cancer therapeutics, especially for MYC-expressing cancers." (PMID 35994503, 2022). "With regard to MYC-dependent cancers, we found a strong SENP6-dependent increase of SUMO2/3 conjugates, revealing that SUMO conjugation is activated either by induction of the SUMO conjugation machinery or by loss of the cellular safeguard deSUMOylase SENP6." (PMID 35022408, 2022). "This method is expected to be useful in identifying the genes that activate MYC, thus allowing the identification of regulatory factors of other proto-oncogenes, as well as in facilitating drug discovery against other malignant tumors driven by oncogenes." (PMID 35887071, 2022). "Overexpression of SIAH2 increases H3K27 acetylation at c-MYC–controlled genes, increases metabolic output, and accelerates cancer cell proliferation." (PMID 36846090, 2022). "Anomalous expression of c-MYC provides cell survival, metabolic adaptations, and uncontrolled cell division characters leading to cancer." (PMID 35401196, 2022). "Consistently, in the present study, CDK16‐KD led to decreased MYC expression and senescence of cancer cells." (PMID 34687270, 2022). "Regarding cancer, as the human TRIB1 gene is located at a chromosomal locus (8q24.13) near the MYC oncogene, it has been associated with multiple cancer types." (PMID 35205759, 2022). "Significant heterogeneity was observed between the three molecular subtypes in cancer-related signaling pathways, including T cell co-stimulation-induced inflammation-promoting pathways, MYC targets v1, MYC targets v2, the G2M checkpoint, and E2F." (PMID 36263125, 2022). "The identification of CHK1 as a putative RelA T505 kinase linked these atypical consequences of NF-κB activity to DNA replication stress, a common feature of cancer cells and to activation of oncogenes such as MYC in particular." (PMID 36240065, 2022). "These extensive investigations have revealed in detail how MYC translocation, amplification, and other upstream perturbations contribute to MYC activity in cancer." (PMID 36018850, 2022). "The therapeutic targeting of BRD4 inhibits BRD4 binding to c-MYC promoter and prevents the expression of MYC-dependent target genes in cancer and inflammatory cells." (PMID 35226658, 2022). "Since MYC and KRAS are often mutated and constitutively expressed in cancer cells, they can be used as therapeutic targets." (PMID 35328482, 2022). "Overexpression of MYC has been shown to contribute to early carcinogenesis in cancers, including prostate and gastric." (PMID 36139061, 2022).